GPR157 (G protein-coupled receptor 157)
Description:
Orphan receptor that promotes neuronal differentiation of radial glial progenitors (RGPs). The activity of this receptor is mediated by a G(q)-protein that activates a phosphatidylinositol-calcium second messenger.
Synonyms: FLJ12132
Tractability: Antibody: UniProt predicts a signal peptide or a membrane-spanning region; its Gene Ontology location is reachable by antibodies, with medium confidence; the Human Protein Atlas places it where antibodies can reach.
Gene: Protein-coding gene on chromosome 1 (9,100,305 to 9,129,122, reverse strand). Ensembl gene ENSG00000180758.
Subcellular location: Cell projection, cilium membrane
Subcellular location (Human Protein Atlas): Cytosol; Plasma membrane
Gene Ontology:
Molecular function: G protein-coupled receptor activity; transmembrane signaling receptor activity
Biological process: adenylate cyclase-activating G protein-coupled receptor signaling pathway; phospholipase C-activating G protein-coupled receptor signaling pathway; radial glial cell differentiation; cell surface receptor signaling pathway; circadian behavior; G protein-coupled receptor signaling pathway; signal transduction
Cellular component: ciliary membrane; membrane
Genetic constraint (gnomAD): Loss-of-function variants: 18 observed, 22.93 expected, observed/expected ratio (o/e) 0.78, 90% interval 0.54 to 1.16. The upper end of that interval is the gene's LOEUF score, 1.16, which puts it in group 5 of 6, group 1 being the genes least tolerant of losing a copy. Missense variants: 440 observed, 452.11 expected, observed/expected ratio (o/e) 0.97, 90% interval 0.9 to 1.05. Synonymous variants: 200 observed, 209.64 expected, observed/expected ratio (o/e) 0.95, 90% interval 0.85 to 1.07.
Homologues: Orthologues: chimpanzee GPR157 (98% identical), macaque GPR157 (94% identical), mouse Gpr157 (85% identical), rat Gpr157 (83% identical), pig GPR157 (80% identical), dog GPR157 (76% identical), guinea pig GPR157 (74% identical), tropical clawed frog gpr157 (58% identical), zebrafish gpr157 (55% identical). Paralogues in human: TMEM116 (20% identical).
Diseases named in the same sentence as GPR157 in open-access papers:
GPR157 is named in the same sentence as 5 diseases in open-access papers, as found by Europe PMC text mining. Sharing a sentence is not in itself a finding about the gene and the disease. The quoted sentences say what the papers report.
breast carcinoma (2 papers, 2022 to 2025). "The results indicated that high expression levels of OPN4, NOS2, GPR157, NCOA2, CLOCK, and TH were associated with shorter OS in breast cancer patients, while high expression of EGR3, NR1H3, RELB, SIAH2, and ADRB1 was linked to improved survival rates." (PMID 41031266, 2025).
Alzheimer disease (1 paper, 2025). A progressive, neurodegenerative disease characterized by loss of function and death of nerve cells in several areas of the brain leading to loss of cognitive function such as memory and language. "In Alzheimer's disease, the hub genes TNFRSF9, LZIC, CD30, SLC45A1, GPR157, and SLC25A33 are implicated in immune regulation, cellular transport, neuronal signaling, and mitochondrial function." (PMID 40104076, 2025).
endometrioid endometrial carcinoma (1 paper, 2025). "Of note GPR157 has been identified as a potential biomarker for endometrioid endometrial carcinoma." (PMID 40871563, 2025).
endothelial dysfunction (1 paper, 2025). In vascular diseases, endothelial dysfunction is a systemic pathological state of the endothelium (the inner lining of blood vessels) and can be broadly defined as an imbalance between vasodilating and vasoconstricting substances produced by (or acting on) the endothelium. "The top hub genes identified were TNFRSF9, LZIC, TNFRSF8, SLC45A1, GPR157, and SLC25A33, which are induced by P. gingivalis and F. nucleatum and are responsible for endothelial dysfunction in brain cells." (PMID 40104076, 2025). "The top hub genes were TNFRSF9, LZIC, TNFRSF8, SLC45A1, GPR157, and SLC25A33, induced by P. gingivalis and F. nucleatum responsible for endothelial dysfunction in brain cells." (PMID 40104076, 2025). "Similarly, our study revealed genes like TNFRSF9, LZIC, TNFRSF8, SLC45A1, GPR157, and SLC25A33 that contribute to endothelial dysfunction in brain cells due to P. gingivalis and F. nucleatum." (PMID 40104076, 2025).
tumor (1 paper, 2025). "GPR157, a G-protein coupled receptor, is gaining recognition for its emerging significance in tumor biology." (PMID 40319860, 2025).